KLF4 (KLF transcription factor 4)
Diseases named in the same sentence as KLF4 in open-access papers (continued):
Sharing a sentence is not in itself a finding about the gene and the disease.
cavernomas (5 papers, 2015 to 2020). "In human vascular lesions and in mice deficient of anyone of the three Ccm genes, KLF4 is strongly upregulated in ECs lining the cavernomas." (PMID 26612856, 2016). "Our dissection of the molecular mechanisms underlying cavernoma pathogenesis unveils KLF4 upregulation as the key initial event in CCM." (PMID 26612856, 2016). "Importantly, in vivo Klf4 genetic inactivation blocks the development and progression of cavernomas and almost completely prevents associated mortality." (PMID 26612856, 2016). "Colocalization of Bst1 and the cavernoma transcripts Klf2, Klf4, and Ly6a using Visium showed concentration of Bst1 progenitor cell transcripts at the level of cavernomas and mulberry lesions." (PMID 33138917, 2020). "Quantification of the number of cavernomas of any size revealed a 70% reduction in iCCM1/KLF4 in comparison with iCCM1 mice." (PMID 26612856, 2016). "Immunohistochemical analysis of brain tissues confirmed BMP6 reduction in ECs lining the cavernomas of iCCM1/KLF4 mice compared to iCCM1 animals." (PMID 26612856, 2016). "At P8, almost 100% of the endothelial cells that lined the cavernomas were KLF4-positive (i.e. bona fide endothelial cells undergoing EndMT), which then declined during the increase in the size of the cavernomas to 70% KLF4-positive cells at P14 and 40% KLF4-positive cells at P30." (PMID 31235698, 2019). "Inhibition of VEGFR2 does not affect the overexpression of KLF2 or KLF4 after CCM2 loss, but it can partially prevent the development of cavernomas in CCM1-deficient animals." (PMID 33348877, 2020).
cerebral cavernous malformation (5 papers, 2016 to 2025). A disorder characterized by malformations in the structure of the capillaries in the brain. "KLF4 is of particular interest because of its reported role in promoting EndoMT in several vascular diseases, including cerebral cavernous malformations, coronary arterial wall damage in Kawasaki disease, and tumor vascular dysfunction." (PMID 37795485, 2023). "Because both KLF2 and KLF4 were shown to be downstream of increased MEKK3-MEK5-ERK5 signaling in cerebral cavernous malformations, we next examined the expression of KLF2 and KLF4 in shear stress-exposed HUVECs." (PMID 37583551, 2023). "The endothelial CCM (Cerebral Cavernous Malformation) complex, comprising KRIT1 (Krev1 interaction trapped gene 1), CCM2 (Malcavernin), and CCM3 (Programmed cell death protein 10), suppresses the expression of KLF2 and KLF4." (PMID 40362576, 2025).
cholangiocarcinoma (5 papers, 2020 to 2025). A carcinoma that arises from the intrahepatic biliary tree (intrahepatic cholangiocarcinoma) or from the junction, or adjacent to the junction, of the right and left hepatic ducts (hilar cholangiocarcinoma). "Similarly, elevated expression of KLF4 enhances proliferation and invasion in cholangiocarcinoma, suggesting that KLF4 acts as a risk factor in this cancer type." (PMID 40487928, 2025). "Among these cancer genes, KLF4 suppresses the proliferation of cholangiocarcinoma, while FBLN2 is an independent protective factor for hepatocarcinoma." (PMID 39920810, 2025). "Interestingly, cholangiocarcinoma’s first line of therapy is represented by 5-FU, and this is consistent with a role played by the axis miR-200b-3p-KLF4 in tumor chemoresistance." (PMID 40863723, 2025). "The inhibition of KLF4-mediated autophagy in cholangiocarcinoma (CCA) cells can be mediated by miR-200b-3p and leads to an increased sensitivity to 5-FU treatment." (PMID 40863723, 2025).
chronic kidney disease (5 papers, 2020 to 2025). Impairment of the renal function secondary to chronic kidney damage persisting for three or more months. "A similar cooperative mechanism between KLF4 and p65 was shown in a mouse model of chronic kidney disease (CKD) with arterial medial calcification, driving phenotypic switching of VSMCs into osteogenic cells." (PMID 41155497, 2025). "Kruppel-like factor 4 (KLF4) has been suggested as a therapeutic target in the context of chronic kidney disease." (PMID 35340414, 2022). "Research showed that Krüppel-like factor 4 (KLF4), a zinc finger transcription factor, can ameliorate chronic kidney disease through mitigating TNF-mediated tissue injury and fibrosis." (PMID 34594474, 2021). "Moreover, Kruppel-like factor 4 (KLF4) acts as an epigenetic modulator in the context of chronic kidney disease." (PMID 37834287, 2023).
chronic lymphocytic leukemia (5 papers, 2017 to 2025). "Examining the correlation between DNA methylation and gene expression revealed that hypermethylation of the KLF4 gene was associated with lower KLF4 expression in fifteen patients with chronic lymphocytic leukemia." (PMID 40589762, 2025). "The recent studies showed that SCGB2A1, KLF4, and PPP1R14B can differentiate a group of circa 5% of cases with less survival in chronic lymphocytic leukemia (CLL) patients, which might be useful for further research about disease prognostication and drug response in CLL." (PMID 34858479, 2021).
colon adenocarcinoma (5 papers, 2013 to 2023). "We found a bacterial regulation of the transcription factors Hes1, Hath1 and KLF4 in the colon adenocarcinoma cell line LS174T, especially by E. coli K-12 and E. coli Nissle 1917." (PMID 23418447, 2013). "Thus, KLF4 was found in colon adenocarcinoma metastasis to the liver and low KLF4 expression was found in poorly differentiated CRC tissues." (PMID 32410997, 2020).
endometrial cancer (5 papers, 2014 to 2025). Primary or metastatic malignant neoplasm involving the endometrium (mucous membrane that lines the endometrial cavity). "The expression of cMYC and KLF4 was found to be upregulated in type I endometrial cancer as compared to type II endometrial cancer." (PMID 40433700, 2025). "In human Ishikawa endometrial cancer cells, MET treatment (60 μM) decreased cell numbers and elicited distinct temporal changes in ESR1, KLF9, PGR, PGR-B, KLF4, DKK1, and other tumor biomarker mRNA levels." (PMID 32046384, 2020). "For example, KLF4 had a hypermethylated CGI shore and gene body and was repressed in three groups of endometrial cancer patients." (PMID 25286960, 2014).
endometriosis (5 papers, 2015 to 2025). The growth of functional endometrial tissue in anatomic sites outside the uterine body. "As shown in the Arid1ad/d mice, eutopic endometrium from women with endometriosis showed increased KLF4 levels compared to control endometrium." (PMID 26378916, 2015). "In addition, some identified hub genes of the EC (TAGLN, GATA6, CDH3, CLU, COL8A1, MYH11, MYOCD) and EU (CXCL13, DDK-1, KLF4, CYP2E1, CYP4B1 and PROK1) have been reported be associated with endometriosis." (PMID 34522169, 2021). "In another study, miRNA 200b was reported to play a role in the pathogenesis of endometriosis by regulating the stem cell phenotype, proliferation, and invasive extension formation in endometriotic cells by targeting ZEB1, ZEB2, and KLF4." (PMID 40572723, 2025).
fibrosis (5 papers, 2011 to 2023). the formation of excess fibrous connective tissue in an organ or tissue in a reparative or reactive process. "Subsequently, a bleomycin-induced fibrosis mouse model was introduced, and it revealed that KLF4 significantly reduced the extent of fibrosis." (PMID 35637963, 2022). "Whole-lung expression of KLF4 was previously reported to be diminished in mice with bleomycin-induced fibrosis, a finding confirmed herein." (PMID 35852857, 2022). "The results revealed that the ratio of Col1 (red or yellow) was lower than that of Col3 (blue) in the KLF4-overexpressing fibrosis model while the ratio of Col1 was higher than that of Col3 and distributed more densely in the control group." (PMID 35637963, 2022). "The study found that the expression of KLF4 and TERT in IPF patients and fibrosis mouse model AT2 is decreased, while the overexpression of KLF4 can increase the expression of TERT and telomerase activity." (PMID 36825939, 2023). "Thus, our results demonstrated that KLF4 could improve the collagen structure arrangement and proportion and decrease α-SMA-positive myofibroblasts in a bleomycin-induced fibrosis mouse model." (PMID 35637963, 2022). "Thus, we speculate that similar to KLF4, KLF6 may play a similar role during RSV infection of the respiratory tract since KLF6 regulates expression of TGF-β, which is involved in lung remodeling and airway fibrosis." (PMID 21849067, 2011).
ischemia (5 papers, 2020 to 2025). A hypoperfusion of the BLOOD through an organ or tissue caused by a PATHOLOGIC CONSTRICTION or obstruction of its BLOOD VESSELS, or an absence of BLOOD CIRCULATION. "KLF4 expression in astrocytes was induced within 3 d of ischemia, as well as in oxygen-glucose deprivation-treated rat primary cortical astrocytes." (PMID 35340414, 2022). "While in the ischemic penumbra, the expression of KLF4 increased slightly during the first 2 days post-ischemia, then increased significantly by day 4, and reached a maximum between 7 and 14 days post-ischemia." (PMID 32264912, 2020). "As expected, KLF4 expression co-localized with Claudin-5 on the cerebral blood vessels in the ischemic hemisphere at days 2 and 7 post-ischemia." (PMID 32264912, 2020). "However, KLF4 was always co-stained well with S100A10 in the penumbra at days 2, 4 and 7 post-ischemia, especially at day 7, KLF4 co-localized with S100A10 extensively." (PMID 36823628, 2023). "While in the ischemic penumbra, the number of KLF4-positive events increased slightly during the first 2 days post-ischemia, then increased significantly by day 4, and reached a maximum between 7 and 14 days post-ischemia." (PMID 32264912, 2020). "KLF4 immunoreactivity was observed in CD31-positive vessels in the ischemic hemisphere at days 2 and 7 post-ischemia." (PMID 32264912, 2020). "Furthermore, KLF4 expression always strongly co-localized with cells expressing high levels of GFAP in the ischemic penumbra at days 2 and 7 post-ischemia, especially at day 7, but this co-localization was markedly disrupted in the ischemic core." (PMID 32264912, 2020). "These ischemia/injury-induced multipotent stem cells (iSCs) expressed not only pericytic markers (e.g., PDGFRβ, neural/glial antigen 2 (NG2), and alpha-smooth muscle actin (αSMA)), but also various stem cell markers (e.g., nestin, c-myc, Klf4, and Sox2)." (PMID 32887241, 2020).
Parkinson disease (5 papers, 2012 to 2024). A progressive degenerative disorder of the central nervous system characterized by loss of dopamine producing neurons in the substantia nigra and the presence of Lewy bodies in the substantia nigra and locus coeruleus. "It is worth mentioning that in Parkinson’s disease model, KLF4 can promote MPP+-induced oxidative stress and neurotoxicity, and then increase neuronal apoptosis and delay the cell proliferation." (PMID 30297986, 2018). "Targeting the PI3K/AKT/KLF4 signaling axis may have therapeutic potential for neuroinflammatory diseases, including Parkinson’s disease." (PMID 37996730, 2024). "Previously, we established two hiPSC lines (WT-iPSC3 and PD-iPSC4) by transduction of retroviral vectors carrying Oct4, Sox2, c-Myc, and Klf4 into the normal human dermal fibroblasts and Parkinson’s disease patient-derived fibroblasts and extensively characterized." (PMID 22911689, 2012).
T-cell acute lymphoblastic leukemia (5 papers, 2014 to 2025). Acute lymphoblastic leukemia of T-cell origin. "Significantly, our studies revealed two breakpoints in the miR-2909-KLF4 axis caused by mutation in the 3′UTR-KLF4 and the altered Zf3 motif sequence, leading to loss of miR-2909 binding to the KLF4 3′UTR and loss of KLF4 binding to DNA sequences in target genes in T-cell ALL subjects." (PMID 25037230, 2014). "Elevated levels of miR-2909 targeted the tumor suppressor gene KLF4 in pediatric B-cell, but not pediatric T-cell ALL, as detected by pMIR-GFP reporter assay." (PMID 25037230, 2014).
adenomyosis (4 papers, 2022 to 2024). The growth of endometrial tissue inside the muscular wall of the uterine corpus. "The downregulation of the JAK2/STAT3 pathway corresponded with the low expression of KLF4 in the endometrial tissue of adenomyosis." (PMID 39886033, 2024). "Krueppel-like factor 4(KLF4), which has been shown to be downregulated in adenomyosis endometrial tissue, governs this process." (PMID 39886033, 2024). "To further explore the expression pattern of KLF4 and autophagy markers in vivo, we used tamoxifen to construct an adenomyosis mouse model." (PMID 35761172, 2022). "KLF4 expression was decreased in endometrial tissues from adenomyosis patients compared with those from fertile controls, especially in stromal compartments." (PMID 35761172, 2022). "We further detected abnormally decreased expression of autophagy markers (LC3-B/LC3-A and Beclin-1) in the endometria of adenomyosis patients and their expression levels weremoderately positively correlated with KLF4 expression levels." (PMID 35761172, 2022). "Similar to the endometrial samples of adenomyosis patients, we detected abnormally decreased expression of KLF4 and autophagy markers (LC3-B/LC3-A and Beclin-1) in the uteri of adenomyosis mice." (PMID 35761172, 2022). "At the same time, we detected abnormally decreased expression of KLF4 protein in the endometrium of infertile patients with adenomyosis." (PMID 35761172, 2022). "The expression level of KLF4 in endometrial stromal cells of patients with adenomyosis was abnormally decreased and it was in an abnormally low autophagy state." (PMID 35761172, 2022). "Endometrial tissues from adenomyosis patients and uteri from an adenomyosis mouse model were collected for the detection of different expression patterns of KLF4 and autophagy markers (LC3-B/LC3-A and Beclin-1) compared with control groups." (PMID 35761172, 2022). "The KLF4 protein level in the endometria of patients with adenomyosis was significantly lower than that in the endometria of normal controls." (PMID 35761172, 2022). "Human endometrial stromal cells (hESCs) isolated from adenomyosis and control endometrial tissues were employed to elucidate the biological functions of KLF4 in autophagy and decidualization." (PMID 35761172, 2022). "Our results suggested that the expression of KLF4 in the endometrium of patients with adenomyosis was decreased." (PMID 35761172, 2022). "The abnormal expression of KLF4 in endometrial epithelial cells and its abnormal autophagy condition may also reduce the ability of the endometrium to accept embryo adhesion in adenomyosis patients." (PMID 35761172, 2022). "The expression of KLF4 in endometrial stromal cells of adenomyosis-infertile patients was significantly decreased, which might be an important reason for the impaired decidualization process." (PMID 35761172, 2022). "In addition, we found that the level of KLF4 in the eutopic endometrium of patients with adenomyosis was abnormally decreased and that the autophagy level was abnormally repressed." (PMID 35761172, 2022). "However, the immunohistochemical results of the endometrium in adenomyosis patients showed that KLF4 and autophagy-related marker expression were reduced in both endometrial stromal cells, but also in endometrial epithelial cells." (PMID 35761172, 2022). "At the same time, KLF4 reversed the poor decidualization of hESCs from adenomyosis patients." (PMID 35761172, 2022). "Contrary to the expression pattern of KLF4, we found that the autophagy levels of endometrial stromal cells were significantly lower in infertile women with adenomyosis (decreased expression of LC3-B/LC3-A and Beclin-1) than in fertile women, similar to other studies." (PMID 35761172, 2022). "Therefore, the expression of KLF4 and the autophagy markers LC3-B/LC3-A and Beclin-1 was abnormally decreased in the endometria of adenomyosis patients, and there was a moderate positive correlation between KLF4 and autophagy markers (LC3-B/LC3-A and Beclin-1)." (PMID 35761172, 2022).
adenomyosis (continued). "Therefore, we hypothesized that abnormally decreased KLF4 expression in patients with adenomyosis leads to low autophagy levels in endometrial stromal cells, which is one of the important reasons for abnormal decidualization." (PMID 35761172, 2022). "KLF4 overexpression increases the autophagy level of hESCs by transcriptionally promoting ATG5 expression, and abnormally decreased KLF4 in adenomyosis impairs hESC decidualization by repressing autophagy." (PMID 35761172, 2022). "Furthermore, immunohistochemical analysis showed that the expression levels of KLF4, LC3-B and Beclin-1 in endometrial stromal cells of patients with adenomyosis were significantly decreased, while LC3-A levels were not decreased." (PMID 35761172, 2022).
Cerebral ischemia (4 papers, 2020 to 2025). Restriction of arterial blood supply to the brain associated with insufficient oxygenation to support the metabolic requirements of the tissue. "In a recent study, we observed that KLF4 inhibited phosphorylation of NF-kB to alleviate the cerebral ischemia-induced cerebral vascular inflammation, and the latter was reported to be involved in the classical activation of astrocytes." (PMID 36823628, 2023). "As KLF4 is a key factor in regulating inflammation, it seems likely that the enhanced KLF4 suppresses the astrocytic expression of C3 after cerebral ischemia." (PMID 36823628, 2023). "In a recent study, we observed that KLF4 inhibited TNF-a-induced activation of NF-kB to alleviate the cerebral ischemia-induced cerebral vascular inflammation." (PMID 36823628, 2023). "Our results demonstrate cerebral ischemia induced activation of A1/A2 astrocytes and upregulated the expression of KLF4 in astrocytes." (PMID 36823628, 2023). "Mechanistic analyses reveal that KLF4 alleviates cerebral ischemia-induced vascular injury by modulating endothelial expressions of CAMs, NF-κB, and TJPs." (PMID 32264912, 2020). "This evidence suggests that KLF4 counteracts cerebral ischemia-induced permeability by increasing TJP expression on the blood vessels." (PMID 32264912, 2020). "It seemed that the enhanced KLF4 could suppress A1 astrocyte expression of C3 but promote the activation of A2-type astrocyte after cerebral ischemia." (PMID 36823628, 2023). "As KLF4 is a key factor in regulating inflammation, it seems likely that the enhanced KLF4 suppresses the cerebral vascular endothelial expression of three CAMs after cerebral ischemia." (PMID 32264912, 2020). "In the current study, we found that in response to cerebral ischemia, the expressions of three CAMs as well as KLF4 were all induced in the ischemic hemisphere following focal cerebral ischemia, but their temporal and spatial expression patterns were different." (PMID 32264912, 2020). "It seemed that the enhanced KLF4 could suppress the vascular endothelial expression of three CAMs including E-selectin, VCAM-1, and ICAM-1 after cerebral ischemia." (PMID 32264912, 2020). "It seems that KLF4 does not directly influence the expression of TNF-α but acts to inhibit TNF-α-induced activation of NF-κB to alleviate the cerebral ischemia-induced cerebral vascular inflammation." (PMID 32264912, 2020).
embryonal carcinoma (4 papers, 2012 to 2023). A non-seminomatous malignant germ cell tumor characterized by the presence of large germ cells with abundant cytoplasm resembling epithelial cells, geographic necrosis, high mitotic activity, and pseudoglandular and pseudopapillary structures formation. "For example, Utf1, a transcription factor required for the proper differentiation of embryonic carcinoma cells and ESCs40, is enriched after chromosome sorting, while Nanog, Oct4 (Pou5f1) and Klf4, although detected, show no significant enrichment in sorted chromosome samples." (PMID 32807789, 2020).